IL6 (interleukin 6)
Diseases named in the same sentence as IL6 in open-access papers (continued):
Sharing a sentence is not in itself a finding about the gene and the disease.
tumor (continued). "Agents blocking IL-6/IL-6R or inhibiting JAK/STAT3 to block tumor progression have been or are being tested in clinical trials, such as siltuximab (an anti-IL-6 mAb), tocilizumab (an anti-IL-6R mAb), Ruxolitinib (a JAK signaling inhibitor)." (PMID 32039001, 2019). "Another immunosuppressive effect is mediated by IL-6 secreted from tumor cells, CAFs, and other tumor stromal cells which leads to MDSC recruitment to the tumor microenvironment." (PMID 31554173, 2019). "The cytokines secreted by tumor cells, such as granulocyte colony-stimulating factor (G-CSF), interleukin (IL)1β, IL6 or tumor necrosis factor (TNF), have been suggested to extend their lifespan." (PMID 31408948, 2019). "The present study demonstrates the inhibitory effects of apigenin through the suppression of IL-6 expression on tumor progression and invasiveness of MDA-MB-231 cells in vitro and in vivo." (PMID 31252615, 2019). "FGF, GM-CSF, IL-6, and IL-10 are growth factors and cytokines well known for playing important roles in promoting tumor progression and/or immune evasion." (PMID 31013891, 2019). "On the other hand, systemic inflammation, which assists tumor grow, is related to the activation of IL-6 and IL-1β pathways which are responsible for induction of SERPINA1 expression." (PMID 31487965, 2019). "SW480- and U87-MG-derived exosomes induce the release of IL-1α, IL-8 and MCP-1 by monocytes, while exosomes released from all tumor cell lines after LPS treatment trigger the production of IL1β, IL-10, IL-6, MIP-1α, MIP-1β and TNF-α cytokines." (PMID 31186484, 2019). "Consistently, inhibition of tumor autophagosome formation or IL-6 secretion by CD4+ T cells markedly retarded tumor growth." (PMID 31300052, 2019). "The adjuvant IL‐7 promoted the vaccine‐mediated anti‐tumour immunity with increased IL‐6 production and decreased T helper type 17 cell differentiations and enhanced CD8 T‐cell expansion." (PMID 31599032, 2019). "In tumor microenvironment, fibroblasts cloud activated by tumor-associated chemokines (e.g., TGF-β, IL-6, and IL-8) and subsequently converted to CAFs." (PMID 30954079, 2019). "The roles of IL-6 and CXCL8 in cancer are often associated with increased tumor cells proliferation, recruitment of MDSCs, angiogenesis, tumor cells stemness." (PMID 30832219, 2019). "Within the tumor microenvironment, several factors lead to the production of IL-6 and IL-8, including IL-1β and TNFα." (PMID 31781510, 2019). "Elevated S100A9 expression in tumor stroma functions as an early recurrence marker in early-stage OSCC patients through increased tumor cell invasion, angiogenesis, macrophage recruitment and IL-6 production." (PMID 30871117, 2019). "One of these is IL-6, a pleiotropic cytokine that participates in acute inflammation, and that also plays a central role in hematopoiesis, tumor progression, and proliferation; in addition, this cytokine has been found within the tumor microenvironment." (PMID 31337349, 2019). "The tumor cells themselves and immune cells surrounding the tumor can release IL‐6, thereby increasing circulating IL‐6 levels." (PMID 31599129, 2019). "Third, several other inflammatory markers related to tumor progression, such as interleukin-6, C-reactive protein, and hypersensitive C-reactive protein, were not included in this study." (PMID 31750248, 2019). "A preclinical study in glioblastoma showed that targeting factors responsible for the myeloid PD-L1 upregulation, such as IL-6 enhance the anti-tumor activity exerted by PD-1 therapy." (PMID 32039024, 2019). "In the case of CCA, interleukins, like IL-6, released by immune cells present in the tumor microenvironment, particularly macrophages, can confer resistance to toxic compounds and promote tumor growth." (PMID 35582588, 2019). "It has been suggested that IL-6 over-production can be either ascribed directly to the tumor or indirectly accounted for by tumoral production of the high circulating norepinephrine levels." (PMID 31137729, 2019).
tumor (continued). "There was a significant correlation between the percentage of IL-6 positive tumor staining and the concentration of IL-6 in the plasma (p = 0.016, r2 = 0.42)." (PMID 31781510, 2019). "IL-6 trans-signaling has been shown to promote aggressive tumor behavior and progression in malignant ascites of ovarian cancer and in breast cancer pleural effusions, and promotes EMT in non-small cell lung cancer, making it an attractive therapeutic target." (PMID 30999958, 2019). "Commonly, activated fibroblasts inhibit early stages of tumor progression through production of fibroblast factors and IL-6 occurring in gap junctions." (PMID 31430935, 2019). "In these mice, tumor formation was inhibited by downregulation of the IL-6 pathway by Itih4 deletion." (PMID 31238892, 2019). "In MM, HIF1-a activity increases glycolytic metabolites, inhibits production of TCA intermediates, and activates IL-6 which all contribute to tumor growth and survival." (PMID 31020046, 2019). "LPS significantly increased Il-6 gene expression at 4 h post-injection for all tumor treatment groups relative to PBS-injected controls (p < 0.05 in all cases)." (PMID 30679700, 2019). "Interleukin-6 has a direct growth stimulatory effect on many tumor cells through the activation of several signaling pathways." (PMID 30741975, 2019). "The present study confirmed that high preoperative serum IL6, IL8, and TNF-α levels were distinctly correlated with the postoperative tumor recurrence risk of HCC patients." (PMID 31781194, 2019). "This is further supported by experiments in mice overexpressing the IL-6 trans-signaling inhibitor sgp130Fc, which show reduced tumor formation in the diethylnitrosamine/3,3′,5,5′-tetrachloro-1,4-bis(pyridyloxy)benzene model of HCC." (PMID 31683891, 2019). "In the same way, the type of tumor removal surgery conducted, as well as changes in weight and pain score, were possible predictors of change in IL-6 concentration after using the app." (PMID 31414667, 2019). "SASP-mediated tumor promotion was inhibited by targeting SASP-derived IL-6 or by depleting Ly6G+ cells." (PMID 31428105, 2019). "The inhibition of IL‐6 curtailed tumor progression similar to 2G8 in NOD SCID mice but the effect was also lost with NK cell ablation." (PMID 31609088, 2019). "IL-6 is a major cancer-promoting factor that activates a variety of pathways involved in tumor growth and tumor cell survival." (PMID 31249807, 2019). "Our findings show that high preoperative serum IL6, IL8, and TNF-α levels were significantly correlated with the postoperative tumor recurrence risk of the HCC patients." (PMID 31781194, 2019). "IL-6 was only expressed in ~ 2% of cells in the trabecular bone of tumor-bearing mice injected with MDA-MB-231GFP/Luc2 cells plus EO-231 cells, corresponding to in vitro results." (PMID 30813947, 2019). "Tumors developed well in nude mice, and tumor tissues were obtained by operation at 28 days after hBMSC, IL-6, or PBS injection." (PMID 30755239, 2019). "A series of cytokines and chemokines can activate STAT3 in tumor cells, among which IL-6 and IL-1β are the major inducers derived from the TME." (PMID 30927928, 2019). "Tumor cells themselves secrete cytokines (e.g. IL-6, granulocyte-macrophage colony-stimulating factor (GM-CSF), VEGF, bFGF) to stimulate angiogenesis and promote tumor growth and dissemination." (PMID 31338489, 2019). "Interleukin-6 is an inflammatory and pleiotropic cytokine, with tumor stimulating and inhibitory effects." (PMID 31174326, 2019). "Enhanced IL-6 signaling has been found to be responsible for cancer development and tumor progression in many human cancers including lung, liver, breast, ovarian, pancreatic, prostate, glioma, lymphoma, melanoma, renal, and colorectal cancers." (PMID 31769418, 2019). "Previous study found that in a UC carcinogenesis mice model, the tumor load of IL-6−/− mice significantly declined than in the wild-type mice." (PMID 31694526, 2019).
tumor (continued). "Several authors have found that serum IL-6 levels are elevated in patients with untreated metastatic or castration-resistant PCa and correlate negatively with tumor survival and response to chemotherapy." (PMID 31390729, 2019). "In fact, protein analysis of the tumor revealed increased IL1β and IL6 content only 12 and 24 h after tumor induction." (PMID 31712726, 2019). "Within the body, many kinds of cells, such as T cells, endothelial cells, macrophages, and tumor cells, can synthesize IL6." (PMID 31781194, 2019). "Illopoulos and colleagues arrived at a similar conclusion, supporting the notion that tumor heterogeneity involves a dynamic equilibrium between stem and non-stem cell compartments, and that this plasticity is regulated by IL-6." (PMID 30691081, 2019). "TNF- α, IL-1, TGF-β, and IL-6 are able to induce the expression of many angiogenic growth factors in tumor such as vascular endothelial growth factor (VEGF)." (PMID 30642295, 2019). "The increased leukocytosis underlines robust cancer-associated systemic inflammation as evidenced also by increased plasma concentration of pro-inflammatory cytokines, e.g. interleukin 6 (IL-6) in the same model of 4T1 tumour-bearing mice." (PMID 30683749, 2019). "IL-6 is highly secreted by tumor cells under hypoxic conditions and serves to attract and activate MSCs." (PMID 31130595, 2019). "IL-6 contributes to tumor growth by increasing DNMT expression and epigenetically repressing tumor suppressor genes or several microRNA in cancer cell lines." (PMID 31114509, 2019). "In human tumor inflammatory microenvironment, IL-6 has also been proved to stimulate the migration and invasion of cancer cells of breast cancer, pancreatic cancer and osteosarcoma." (PMID 31766991, 2019). "Nevertheless, IL-6 promotes antitumor effect by boosting T-cell immunity and by trafficking antitumor T cells to lymph nodes and tumor sites, executing the cytotoxic effects." (PMID 30885232, 2019). "Profiling of cytokines in ascitic fluids isolated from patients uncovered the presence of pro- inflammatory molecules, among which IL-6 and TNFα were suggested as critical mediators of tumor cell survival." (PMID 31817625, 2019). "Importantly, also Stat6-deficient tumor epithelia were characterized by increased Stat3 phosphorylation suggesting that enhanced gp130-dependent Stat3 activation triggered by IL-6 and IL-11 could account for the pro-proliferative, pro-tumorigenic phenotype of Stat6−/− mice (data not shown)." (PMID 30353167, 2019). "Direct regulation of tumor cell survival by IL-6 involves inactivation of pro-apoptotic molecules and regulation of anti-apoptotic protein expression." (PMID 31817625, 2019). "In fact, in our study, pro-inflammatory cytokine production, such as IL1β and IL6, was blocked after 24 h of tumor induction." (PMID 31712726, 2019). "In an ovarian cancer mouse model, omental adipocytes promote tumour cell homing to omentum after intraperitoneal tumour cell injection through the actions of interleukin (IL)-8, IL-6, MCP-1, and adiponectin secreted by omental adipocytes." (PMID 31334678, 2019). "Polarization of macrophages towards M2 phenotype is supported by an immunosuppressive cytokine milieu composed of tumour- and stromal-derived factors that include TGFβ, IL-6 and IL-1032,41–43." (PMID 31439856, 2019). "Increased tumor incidences in Brg1IEC-AKO mice were associated with the persistent inflammation, as reflected by increased IL-6, IL-1β, TNFα and CCL2 productions in the 5 months of AOM-treated Brg1IEC-AKO mice." (PMID 31601814, 2019). "IDO1 induces the expression of pro-tumoral cytokines such as IL-6, which recruits MDSCs at the tumor site." (PMID 30708988, 2019). "We found that the number of IL-6- and IL-8-positive tumour cells was significantly increased in tumour tissues in comparison with matched adjacent tissues." (PMID 31324197, 2019).
tumor (continued). "In NSCLC, elevated EGFR activity is associated with induction of IL-6 transcription, which in turn drives autocrine IL-6 signaling and tumor proliferation." (PMID 31741710, 2019). "For example, peri-tumor tissue-sourced fibroblasts secrete various cytokines, including IL-6, CXCL1, CCL2, SCGF-β, CXCL8 and HGF, to recruit cancer stem cells, maintain cancer stemness and promote intrahepatic metastasis of HCC." (PMID 30999932, 2019). "On D7, IL-6 and IL-9 were isolated from the network, which seemed to have regenerative function and anti-tumor effect, respectively." (PMID 31751357, 2019). "Tumor cells produce numerous chemokines that attract macrophages, which are capable of producing an assorted array of cytokines, such as IL6 all of which dictate the fate of a developing tumor." (PMID 30927925, 2019). "Hariharan found that IL6 secreted by adipose tissue influenced the migration of BT cells and enhanced tumor progression." (PMID 31809208, 2019). "Early production of TNF-α, IL-1β, and IL-6 in the liver after DEN treatment correlated with tumor development in AIRmax mice." (PMID 31049358, 2019). "In the tumor microenvironment, IL-6/JAK–STAT3 signaling promotes proliferation, invasiveness, and metastasis of tumor cells, while strongly suppressing the antitumor immune response." (PMID 31703694, 2019). "In contrast, IL-6 secretions were the highest in pancreatic cell cultures from tumor-bearing mice, and they were substantially lower in all other groups of mice." (PMID 31878338, 2019). "The regulatory effect of SI-CLP is not clear yet since the cytokines induced by SI-CLP can either promote (IL-1β, IL-6, IL-13) or suppress (IL-12) tumor progression." (PMID 32038607, 2019). "Consistent with the in vitro findings, NANOG knockdown abolished the tumor-enhancing effect of IL-6." (PMID 30804456, 2019). "Considering the role of IL-6 in tumor initiation or metastasis as inducing EMT141,142, we can argue a collaborative relationship between RASSF1A depletion, YAP nuclear accumulation, and elevated IL-6 in carcinogenesis." (PMID 31804463, 2019). "Below, we direct the reader to several studies that highlighted the role of lysophosphatidic acid (LPA), extracellular matrix (ECM) fragments, interleukin 6 (IL-6), and tumor necrosis factor alpha (TNFα), in the regulation of detached tumor survival." (PMID 31817625, 2019). "Tumor cells and tumor-derived factors (such as GM-CSF and IL-6) can induce the accumulation of MDSCs in PBMCs from healthy donors." (PMID 31231374, 2019). "Malignant epithelial cells secrete cytokines, such as TNFα, IL-6, and IL-11, which inhibit the differentiation of the fibroblasts that surround tumor cells into adipocytes and increase their aromatase activity and expression." (PMID 31412584, 2019). "Tnf-α, Il-1β, and Il-6 mRNA decreased in multiple brain regions of LPS-treated tumor-bearing mice relative to LPS-treated controls; tumor resection attenuated these effects in some cases (but not Tnf-α)." (PMID 30679700, 2019). "IL-6 is one of the most versatile cytokines involved in the regulation of immune responses and the promotion of tumor development." (PMID 31795965, 2019). "Monocytes have been shown to be cytotoxic to tumor cells in the presence of pro-inflammatory cytokines such as Interferon Alpha, Interferon Gamma, and IL-6." (PMID 30871636, 2019). "For example, macrophages exposed to IL-4, IL-10, and IL-13 differentiate into the M2 phenotype during tumor progression and secrete IL-4, IL-5, and IL-6 to enhance angiogenesis, immunosuppression, and matrix remodeling." (PMID 31192126, 2019). "Activation of S1PR4 primed apoptotic tumor cell-stimulated macrophages for signaling via the nerve growth factor receptor TrKA, which induced among others IL-6 and IL-10 expression." (PMID 31379883, 2019).
tumor (continued). "The expression levels of miR‐206 were dramatically reduced in tumour tissues compared to healthy participants' normal lung tissues, whereas the levels of serum IL‐6 were significantly increased in NSCLC patients." (PMID 31507089, 2019). "Significant differences in IL-6 serum levels between healthy donors and BC patients at early stage are also reported, showing also a progressive trend related to tumor stage." (PMID 30658426, 2019). "To address the physiological relevance of this finding, we treated RCC cells in vitro with IL-6, a tumor microenvironment known to activate STAT3." (PMID 30796200, 2019). "It is well documented that IL-6 plays a central role in tumor progression due its ability to promote cell proliferation and inhibit apoptosis." (PMID 31089160, 2019). "Exercise induces the secretion of IL-6 from muscle tissues and mobilizes and redistributes IL-6-sensitive natural killer cells to tumor microenvironments through β-adrenergic signaling." (PMID 30754663, 2019). "Accordingly, we examined the relationships of CSC marker and IL-6 expression levels with tumor burden, to inform innovative future treatment approaches." (PMID 31315262, 2019). "Ablation or blocking of IL-6 signaling resulted in reduced tumor growth in absence or presence of COPD-like airway inflammation and in mice constitutively expressing IL-17A in the lung epithelium." (PMID 31316109, 2019). "LPS stimulation of tumor hepatocytes further enhanced the expression of inflammatory cytokines and chemokines Ccl2, Cxcl1, Cxcl2, Tnfa, and Il6." (PMID 30990169, 2019). "To validate these data further, we analyzed public databases for the association of the expression of “IL-6, PTGER2, and PTGER4” with aggressive tumor phenotypes." (PMID 31014367, 2019). "IL-6 mediates STAT3 activation in tumor and tumor progression, and IL-6 neutralization reduces STAT3 activity in vivo." (PMID 31533774, 2019). "Among proinflammatory cytokines, several studies have reported that the pleiotropic cytokine interleukin-6 (IL-6), which is produced by various cell types, contributes to the inhibition of the apoptosis and proliferation of tumor cells." (PMID 31795177, 2019). "Increasing evidence has revealed that IL-6 promotes tumour development through the STAT3 signalling pathway." (PMID 31324197, 2019). "Taken together, our findings identify IL-6Rα as a direct target of MH and its flavonoids, highlighting IL-6R blockade as a mechanism for the anti-tumor activity of MH, as well as a viable therapeutic target in IL-6-dependent cancers." (PMID 31491838, 2019). "HOTTIP was noted to promote the expression of IL-6 by binding to c-jun, which resulted in a promoted PD-L1 expression in neutrophils and immune escape while inhibiting T cell proliferation as well as tumor immunotherapy." (PMID 31533774, 2019). "MSC-derived IL-6 protects tumor cells from doxorubicin-induced apoptosis by activating STAT3 signaling." (PMID 30927928, 2019). "These microvesicles were taken up by macrophages, where miR let-7b targeted the pro-inflammatory cytokine IL-6 to attenuate tumor inflammation." (PMID 31766495, 2019). "From our analysis, we identified IL-2, IL-6, and TGFβ as the cytokines most significantly modulated by the tumor itself and by RT." (PMID 30658426, 2019). "US28 promotes angiogenesis and tumor formation via COX-2 induced production of IL-6, phosphorylation of STAT-3, and activation of nuclear factor-kappaB." (PMID 31203442, 2019). "Previous studies have shown that IL-6 signaling induces dysfunctional immune system responses in the tumor microenvironment." (PMID 31315262, 2019). "IL-1 signaling has been reported in various studies (including our own) to be associated with poor prognosis due to the resulting downstream expression of genes involved in tumor progression including IL-6 and IL-8." (PMID 30890189, 2019). "Conversely, inhibition of the IL-6/JAK/STAT3 pathway reduces tumor cell proliferation and restores sensitivity to AR-targeted drugs." (PMID 31143708, 2019).